ARGLU1-DT (ARGLU1 divergent transcript)
Synonyms: LINC00443; LINC00551
Gene: Long non-coding RNA gene on chromosome 13 (106,567,330 to 106,716,679, forward strand). Ensembl gene ENSG00000272274.
Diseases named in the same sentence as ARGLU1-DT in open-access papers:
ARGLU1-DT is named in the same sentence as 7 diseases in open-access papers, as found by Europe PMC text mining. Sharing a sentence is not in itself a finding about the gene and the disease.
ARGLU1-DT shares sentences with these, for which no sentence is quoted: tumor (6 papers); lung adenocarcinoma (4); cancer (2); esophageal squamous cell carcinoma (2); lung carcinoma (1); preeclampsia (1); renal carcinoma (1).